ACSL3 (acyl-CoA synthetase long chain family member 3)
Diseases named in the same sentence as ACSL3 in open-access papers (continued):
Sharing a sentence is not in itself a finding about the gene and the disease.
osteosarcoma (1 paper, 2023). A usually aggressive malignant bone-forming mesenchymal neoplasm, predominantly affecting adolescents and young adults. "Data in this study fills some of the gap in understanding the post-transcriptional regulatory mechanisms of ACSL3 and provides new insights into the mechanisms of lipid metabolism regulation and its effect on susceptibility to ferroptosis in osteosarcoma cells." (PMID 37993451, 2023). "Specifically, ACSL3 is generally scattered in the nucleus or cytoplasm in osteosarcoma cells, but when BRD4 is interfered, ACSL3 is more dispersed in the cytoplasm with a decrease in overall protein levels." (PMID 37993451, 2023). "Conversely, knocking down ACSL3 in osteosarcoma cells overexpressing BRD4 revealed that the accumulation of arachidonic acid and erastin-ferrop induced by BRD4 can be further attenuated by ACSL3 inhibition." (PMID 37993451, 2023). "In this study, we first determined the contribution of BRD4 and ACSL3 to erastin- induced ferroptosis in osteosarcoma cells, and then elucidated the effects and regulation mechanisms of BRD4 on pre-mACSL3 splicing and expression." (PMID 37993451, 2023). "The expression vectors of ACSL3 with the full-length transcript, the AMP-binding domain-loss transcript (△113 ~ 587 aa), and the two common ACSL3 exon skipping transcripts with a flag tag were constructed and transfected into osteosarcoma cells respectively." (PMID 37993451, 2023). "Finally, 18 paired osteosarcoma tissues and normal osteogenic tissues were selected from the GEO database (cancerous tissue matched 1:1 with adjacent osteogenic tissue, GSE99671) to analyze the expression correlation between BRD4, SRPK2, SRSF2 and ACSL3." (PMID 37993451, 2023). "It shows that the expression of ACSL3 was not correlated with the expression of BRD4 and SRPK2, but positively correlated with SRSF2, which is consistent with our findings in 10 cancerous tissues surgically removed from patients with osteosarcoma." (PMID 37993451, 2023).
polio (1 paper, 2013). "On the other hand, it is possible that the inhibition of polio replication resulted from the excess of Acsl3 activity in the cells over-expressing GFP-Acsl3-HA construct." (PMID 23762027, 2013).
rectal cancer (1 paper, 2025). A primary or metastatic malignant neoplasm that affects the rectum. "Importantly, ACSL3 protein levels were also significantly greater in radioresistant human primary rectal cancer tissues than in their nonirradiated controls." (PMID 40102409, 2025).
schwannoma (1 paper, 2024). A benign, usually encapsulated slow growing tumor composed of Schwann cells. "Partial knockdown of ACSL3 via doxycycline-inducible shRNA constructs impairs proliferation of NF2-KO cells in cell culture and also significantly impairs the growth of NF2-KO schwannoma xenografts." (PMID 38879607, 2024).
tongue cancer (1 paper, 2022). A malignant neoplasm affecting the tongue. "Among them, AC099850.3 is the most co-expressed lncRNA, which is related to six differently expressed mRNAs, namely (CAV1, NRAS, ACSL3, AURKA, EIF2AK4 and RRM2), and its high expression level is closely related to the reduction in the survival rate of patients with tongue cancer." (PMID 35299954, 2022).
viral infection (1 paper, 2013). "It is possible that GFP and/or HA tags of the fusion protein specifically interfered with the Acsl3 function required to support the viral infection." (PMID 23762027, 2013).
ZIKV infection (1 paper, 2018). "The topological analysis on the extended network identified SH2B adaptor protein 3 (SH2B3), FGFR10P2, ACSL3, OPTN, SAMD8, and TNFRFS13B as additional key molecules associated with ZIKV infection." (PMID 30046058, 2018).
cancer (64 papers, 2008 to 2025). A tumor composed of atypical neoplastic, often pleomorphic cells that invade other tissues. "More importantly, increasing evidence suggests that ACSL3 upregulation is associated with various diseases, including cancer." (PMID 39744125, 2024). "ACSL3 is closely associated with tumorigenesis and malignant progression in a variety of cancers 37-40." (PMID 35414781, 2022). "Low ACSL3 expression is associated with increased sensitivity to ferroptosis in all cancer cell types, exogenous MUFAs and ACSL3 activity specifically promote the cellular status of antiferroptosis." (PMID 34499810, 2021). "Tumorigenesis risk is associated with upregulated periodic cancer cell cycle genes (Fkbp5, Acsl3) and enzymatic mutagenesis genes (Cy3a44)." (PMID 34202278, 2021). "We also found that overexpression of LPIAT1 causes enhanced cancer cell proliferation and increased colony formation, an effect that was rescued by knocking down ACSL3." (PMID 32034305, 2020). "Notably, ANGPTL4 has been significantly associated with various cancers, and ACSL3, crucial for fatty acid metabolism, exhibits altered expression levels in cancer, signalling aggressive tumour behaviour and a poor prognosis." (PMID 37556076, 2023). "An exploration using public databases found that not only do ACSL3 and 4 play a pivotal role in fatty acid metabolism in normal tissues, but they are also frequently expressed at altered levels in cancer, which is sometimes associated with more aggressive metastasis and poor prognosis." (PMID 36497375, 2022). "Numerous cancers have ACSL3 overexpression, which is linked to a poor prognosis." (PMID 36338658, 2022). "Moreover, our data propose that metabolic reprogramming is associated with an ACSL3 increase in cancer cells." (PMID 33030783, 2020). "Either Acsl3 knockout or suppression of tumor-derived Pai-1 hinders the expansion of cancer-associated fibroblasts and extracellular matrix deposition and hampers the infiltration of immunosuppressive cell populations in tumors, including M2-like macrophages and Tregs." (PMID 33127675, 2020). "Therefore, the upregulation of Acsl3 in the CS group suggested that cigarette smoke exposure could increase the risk of cancer." (PMID 36232309, 2022). "Therefore, in order to understand more completely how fatty acid metabolism is compartmentalised in cancer cells, it is first necessary to determine the organelle-association patterns for endogenously ACSL3 and ACSL4 in different cancer subtypes and cell lines." (PMID 29450800, 2018). "We found that ACSL3 KO significantly inhibited LD production, whereas OA increased LD accumulation in radioresistant cancer cells." (PMID 40102409, 2025). "Together, these results indicate that ACSL3 plays an important role in mediating ferroptosis resistance in radioresistant cancer cells." (PMID 40102409, 2025). "Conversely, the function of ACSL3 in cancer seems to hinge on the specific type and stage of the disease." (PMID 40932861, 2025). "Western blotting results demonstrated that ACSL3 was the only protein significantly increased in RR cancer cells (A549-RR, H1299-RR, SW837-RR, and CMT93-RR) compared with their corresponding parental cells." (PMID 40102409, 2025). "ACSL3, a pivotal enzyme in lipid metabolism, exhibits a dual function—facilitating cancer development while suppressing ferroptosis—highlighting the intricacies of metabolic reprogramming in tumour advancement and medication resistance." (PMID 41158124, 2025). "For example, ACSL4 is a positive regulator of ferroptosis, whereas ACSL3 contributes to the acquisition of ferroptosis resistance in cancer cells." (PMID 40102409, 2025). "ACSLs also regulate metabolism in a cancer type‐specific manner: ACSL3 drives FAO in opposing directions in BC and NSCLC, while supporting proliferation in both cancer types." (PMID 39853696, 2025).
cancer (continued). "To investigate the relationship between ACSL3-induced LD synthesis and ferroptosis, we generated stable ACSL3-overexpressing (OE) SW837 and CMT93 cells, and confirmed that ACSL3-OE significantly increased LD formation in cancer cells." (PMID 40102409, 2025). "The acyl-CoA synthetase long-chain family member 3 (ACSL3), which is critical in converting fatty acids into fatty acyl-CoA esters, enables cancer cells in the lymph to incorporate oleic acid in the cell membrane to protect them from ferroptosis." (PMID 39211044, 2024). "This promotion is achieved by suppressing the trimethylation of histone H3 at lysine 4 (H3K4me3), reducing the expression levels of ACSL3, and clinical evidence demonstrates that ACSL3 downregulation benefits the prognosis of cancer patients." (PMID 38397398, 2024). "Subsequently, pre-mACSL3 splicing mediated by BRD4 and SRPK2 ensures the expression abundance of ACSL3 in cancer cells." (PMID 37993451, 2023). "Intercellular MUFA trafficking between adipocytes and cancer cells also contributes to ferroptosis resistance and is mediated by ACSL3." (PMID 36776554, 2023). "Taken together, our results suggest that the reduction of extracellularly derived lipids, either by serum lipid depletion or ACSL3 inhibition, triggers an increase in autophagic flux, possibly to replenish cancer cells with the necessary lipids." (PMID 34998392, 2022). "In NSCLC, the overexpression of ACSL3 increases fatty acid activation, leading to more aggressive and invasive cancers and consequently a poorer outcome for patients." (PMID 36497375, 2022). "Additional studies are needed to better understand ferroptosis and anti-cancer immunity and how to target ACSL3 or ACSL4 for better immunotherapeutic efficacy." (PMID 36497375, 2022). "The Wilcoxon test was used to look for differences in the expression of ACSL3 in seventeen types of cancers and normal tissues, using the TIMER online database." (PMID 36338658, 2022). "Acsl3 increases the proliferation, migration, and invasion of tumor cells by increasing fatty acid β-oxidation, which is conducive to the occurrence of malignant tumors." (PMID 36232309, 2022). "According to recent studies, ACSL3 is over-expressed in most cancer types and mainly promotes the development of cancer in different ways." (PMID 36497375, 2022). "Knockdown of ACSL3 inhibits fatty acid synthesis in primary hepatocytes and its suppression perturbs fatty acid oxidation in cancer cells." (PMID 33369888, 2021). "It is noteworthy that the ferroptosis suppressor genes, SLC3A2, FANCD2, CISD1, and ACSL3, were upregulated in most cancer types, indicating that ferroptosis was generally inhibited in cancers." (PMID 34434214, 2021). "In conclusion, previous studies have reported that PHKG2, PEBP1 and NCOA4 are positive regulators that promote ferroptosis in some kinds of cancers, whereas the remaining two genes (ACSL3 and CISD1) suppress ferroptosis in cells." (PMID 34115610, 2021). "Knockdown of ACSL3 in NSCLC cell lines results in reduced cancer cell proliferation, while its deletion in mice suppresses KrasG12D-driven tumor initiation." (PMID 32034305, 2020). "ACSL3 can promote cancer cell survival through amplified fatty acid β-oxidation and increased arachidonic acid-dependent prostaglandin synthesis, both of which can drive tumour growth." (PMID 32286604, 2020). "Together, 183 proteins changed upon FGF19 treatment that were involved in different aspects of metabolism (e.g. Acot2, Acox1 and Acsl3) and 267 in cell survival/cancer (Col6a3." (PMID 28178326, 2017). "In addition, ACSL3, an enzyme catalyzing esterification of MUFAs with coenzyme A, is also upregulated in radioresistant cancer cells." (PMID 40102409, 2025).
cancer (continued). "Consequently, we propose that targeting ACSL3 and inducing ferroptosis should be considered a novel therapeutic strategy for overcoming cancer radioresistance." (PMID 40102409, 2025). "These contradictory findings suggest that ACSL3 might play varying roles depending on the cancer stage." (PMID 40932861, 2025). "Notably, ACSL3 KO significantly enhanced the antitumor effects of erastin (or RSL3) in these cancer cells." (PMID 40102409, 2025). "Mechanistically, OA promotes ferroptosis resistance in radioresistant cancer cells in an ACSL3-dependent manner via a reduction in the amount of PUFA-PLs in cell membranes and inhibition of lipid peroxidation and subsequent ferroptosis, leading to cancer radioresistance." (PMID 40102409, 2025). "Our data revealed that ACSL3 was obviously increased in radioresistant cancer cells." (PMID 40102409, 2025). "First, we determined whether ACSL3 participates in LD formation in irradiated cancer cells exposed to exogenous FAs." (PMID 40102409, 2025). "Inhibition of ACSL3 reduces the sensitivity of cancer cells to ferroptotic cell death." (PMID 36942991, 2023). "Interestingly, other studies have revealed that ACSL3 is also necessary to protect cancer cells from ferroptosis, by promoting the incorporation of SFA and MUFA." (PMID 35912247, 2022). "For example, its expression may vary in the different stages and types of cancer: ACSL3 was increased in early carcinogenesis to promote lipid anabolism and deposition, but deceased in advanced breast and prostate cancer to increase lipid utilization." (PMID 36507355, 2022). "Some researchers are also concerned about the close relationship between ACSL3 and cancer." (PMID 36338658, 2022). "Furthermore, we present a perspective on cancer therapies targeting or combining ACSL3 and ACSL4 in ferroptosis." (PMID 36497375, 2022). "In addition, ACSL4 is a positive regulator in ferroptosis, whereas ACSL3 contributes to cancer cells acquiring ferroptosis resistance." (PMID 36497375, 2022). "While MUFA-induced ferroptosis is dependent on ACSL3, ACSL3 converts MUFAs to acyl-CoA esters that bind to membrane phospholipids and reduce the sensitivity of plasma membrane lipids to lethal oxidation, thereby protecting cancer cells from ferroptosis attack." (PMID 36313359, 2022). "It was reported that ACSL3 has relatively complex functions in different types of cancer." (PMID 36507355, 2022). "Moreover, overexpression of ACSL3 increases cell proliferation, migration, and invasion, altering the metabolic properties of cancer cells." (PMID 33030783, 2020). "Importantly, there is emerging evidence that dysregulated expression of both ACSL3 and ACSL4 is associated with disease and especially with cancer." (PMID 32286604, 2020). "Whether the overexpression of ACSL3 is sufficient to increase synthesis of prostaglandins and promote cancer proliferation remains to be investigated." (PMID 32034305, 2020). "ER stress triggers cancer cell death in many contexts, therefore ER stress inducers together with ACSL3 inhibition could result in enhanced antitumor response." (PMID 31344914, 2019). "Some recent reports link ACSL3 and an unfolded protein response in cancer." (PMID 31344914, 2019). "Among ACSL family, ACSL3 was found to be overexpressed in different types of cancer." (PMID 31513595, 2019). "In addition to their key gatekeeper roles in fatty acid metabolism in normal tissues, ACSL3 and ACSL4 expression levels are frequently altered in cancer, and this is sometimes associated with a more aggressive metastatic phenotype and a poor prognosis." (PMID 29450800, 2018).
cancer (continued). "In addition, OA also failed to protect ACSL3-deficient cancer cells from erastin (or RSL3)-induced lipid ROS elevation and a decrease in the GSH/GSSG ratio." (PMID 40102409, 2025). "It is still necessary to investigate in depth the mechanism by which ACSL3 and 4 participate in the ferroptosis process of tumor cells, as well as the related regulatory factors, in order to develop a better theoretical basis for therapies targeting malignant tumors." (PMID 36497375, 2022). "Hence, the status of ACSL3-LPIAT1 axis in human lung tumors may serve as a biomarker for personalized anti-cancer treatment." (PMID 32034305, 2020). "Among these, PEBP1/STK11 co-expression strongly negatively correlates in all cancer types with enzymes that increase the biosynthesis of fatty acids such as members of the ACSL family (ACSL1, ACSL3, ACSL4, ACSL5, and ACSL6)." (PMID 40806276, 2025). "PPAR signaling pathway has been previously reported to be regulated by NAT10 through ac4C modification of genes such as ELOVL6, ACSL1, ACSL3, ACSL4, ACADSB, and ACAT1, thus modulating fatty acid metabolism in cancer cells." (PMID 40123006, 2025). "Recent studies have identified crucial roles of ACSL1, ACSL3, and ACSL4 in ferroptosis, thereby opening new avenues for exploring their involvement in tumorigenesis and cancer therapy." (PMID 41288931, 2025). "As a result, the inactivation of the enzymes involved in MUFA-PL synthesis, such as stearoyl-CoA desaturase 1 (SCD1) and acyl-CoA synthetase long-chain family member 3 (ACSL3), sensitizes cancer cells to ferroptosis." (PMID 38428031, 2024). "Thus ACSL3 may be interesting as a possible target for cancer therapy more broadly." (PMID 38879607, 2024). "ACSL3, AIFM2, HSD17B7, LPCAT1, LSS, PLIN3 and RAB10 were up-regulated with the progression of cancer stage of HCC patients, while CIDEB, G0S2, HSD17B13, PLIN1 and PLIN2 were down-regulated." (PMID 37464334, 2023). "RNA‐seq data from our study showed decreased expression of ACSL1, ACSL3 and ACSL4 in NAT10‐depleted cancer cells, which further confirmed that the mRNA transcripts of these genes are controlled by NAT10‐dependent ac4C mRNA acetylation." (PMID 36149760, 2022). "Acyl-CoA synthetase long chain 3 (ACSL3), an upstream enzyme of CPT1, which converts free FAs into fatty acyl-CoAs, is also crucial for the proliferation of KRAS-driven cancer cells." (PMID 36172157, 2022). "The dysregulation of ACSL3 and ACSL4, which belong to the long-chain fatty acyl CoA synthetase family (ACSLs), affects the behavior of various cancer cells." (PMID 36497375, 2022). "ACSL3 mediates the EMT and metastasis of CRC cells by activation of the FAO pathway to produce ATP and NADPH, which sustain redox homeostasis and fuel cancer cells for invasion and distal metastasis." (PMID 35414781, 2022). "Here, we present a summary of the current knowledge on ACSL3 and ACSL4 and their functions in various cancers." (PMID 36497375, 2022). "We presented the top 30 correlations between CTRP drug sensitivity and mRNA expression of ACSL3 and EPAS1 in pan cancer, as well as the correlation between GDSC drug sensitivity and mRNA expression of ACSL3 and EPAS1 in pan cancer." (PMID 35223835, 2022). "In KPC;Acsl3+/+ pancreatic tissue, PAI-1 was mainly localized in cancer cells (colocalization score PAI-1/basic cytokeratin: 78.27 ± 4.11%) and appeared enriched at their periphery and in close contact with the adjacent stromal cells (insets)." (PMID 33127675, 2020). "Our data show that cancer cell lines that are sensitive to ACSL3 knockdown are also sensitive to LPIAT1 knockdown, while others that are resistant to ACSL3 knockdown are also resistant to LPIAT1 knockdown." (PMID 32034305, 2020).